PNPLA3 (patatin like domain 3, 1-acylglycerol-3-phosphate O-acyltransferase )
Diseases named in the same sentence as PNPLA3 in open-access papers (continued):
Sharing a sentence is not in itself a finding about the gene and the disease.
steatosis (continued). "Furthermore, the PNPLA3 genotype seems to also influence steatosis development in patients with hepatitis B and hepatitis C and alcohol abuse, and it has been independently associated with the progression of hepatitis, including fibrosis, cirrhosis, and HCC occurrence." (PMID 27247565, 2016). "However, the role of PNPLA3 rs738409 SNP on liver fibrosis and steatosis, portal hypertension, and virological response in HIV/HCV coinfection remains unclear." (PMID 26599080, 2015). "Again, PNPLA3 148M/M (estimate +0.07±0.03, p = 0.032) and the interaction with older age at infection (estimate +0.07±0.03, p = 0.045) remained significantly associated with FPR independently of the steatosis severity (grade 2–3 vs. 0–1; estimate +0.04±0.02, p = 0.03)." (PMID 25171251, 2014). "Obviously, only a case control study could assess if the higher prevalence of carotid atherosclerosis observed in NAFLD compared to individuals without steatosis, is related to an higher prevalence of PNPLA3 genotype and risk of cardiovascular disease." (PMID 24069270, 2013). "Importantly, the association between PNPLA3 genotype and steatosis is independent of insulin resistance and serum lipids concentration, but appears to modify response to nutritional and lifestyle factors including obesity." (PMID 23394097, 2013). "Recently, our model in which PNPLA3 I148M sequesters ABHD5 to initiate steatosis was evaluated by the group of Hobbs and Cohen and provided additional evidence that overexpression of ABHD5 can reduce steatosis induced by PNPLA3 I148M." (PMID 39814233, 2025). "Our objective was to analyze the relationship between PNPLA3, TM6SF2, and MBOAT7-TMC4 and steatosis, steatohepatitis, and liver fibrosis in PLWHIV with NAFLD." (PMID 36110512, 2022). "However, it is unclear whether these associations are independent of the association with the PNPLA3 rs738409 shown to be significantly associated with steatosis and ballooning in the same study." (PMID 26462272, 2015). "Recently, an interaction between PNPLA3 and IL28B genotypes in the development of steatosis has been described." (PMID 26389885, 2015). "Conversely, under a high-fat diet, hepatic fat levels in Pnpla3 I148M mice remained unchanged, and steatosis was absent." (PMID 40004054, 2025). "We observed genotype-specific differences in response to resmetirom consistent with this, demonstrating that steatosis, stellate cell activation, and secretion of the pro-fibrotic marker COL1A1 were significantly reduced in the PNPLA3 wild-type LAMPS compared to the GG LAMPS." (PMID 39324073, 2024). "We next interrogated the interplay between PNPLA3 genotypes and FFA-induced steatosis." (PMID 36823355, 2023). "Neither Pnpla3 genetic defect nor Pnpla3 wild-type (wt) over-expression in mice prompts steatosis, while mice carrying the p.I148M knock-in (KI) acquire fatty-laden hepatocytes upon a high-sucrose diet challenge." (PMID 34680476, 2021). "Animal models of Pnpla3 knockout do not exhibit hepatic TG accumulation hence do not develop steatosis." (PMID 31062641, 2019). "Mice overexpressing human wild type PNPLA3 have TG levels similar to the non-transgenic mice, although PNPLA3-I148M overexpression recapitulates the human steatosis phenotype." (PMID 31062641, 2019). "Liver fibrosis and steatosis—staged by liver biopsy and transient elastography using the Controlled Attenuation Parameter (CAP)–and portal hypertension (hepatic venous pressure gradient, HVPG) were compared across PNPLA3 genotypes." (PMID 26599080, 2015). "Multivariate analysis revealed that the factors associated with steatosis in overweight CHC patients included age (OR/CI:1.023/1.001–1.045, P = 0.04) and diabetes (OR/CI:2.201/1.055–3.875, P = 0.03), but not PNPLA3 rs738409 genotype variants." (PMID 26139292, 2015). "We aimed to assess whether GCKR rs780094 C→T SNP influences the expression of steatosis, lobular inflammation and fibrosis in NAFLD patients, after correction for PNPLA3 genotype." (PMID 24498332, 2014).
steatosis (continued). "There is a significant interaction between age at infection and PNPLA3 genotype in determining fibrosis progression, but the association between PNPLA3 and FPR is independent of the histological severity of steatosis." (PMID 25171251, 2014). "A previous study, also reported an association between IL28B rs12980275 genotype and steatosis in CHC non genotype 3 patients, but the rs12979860 IL28B polymorphism was not tested and the interaction with PNPLA3 genotype was not analyzed in details." (PMID 23394097, 2013). "A nonsynonymous single nucleotide polymorphism rs738409 (I148M) in patatin-like phospholipase domain-containing protein 3 (PNPLA3) predisposes susceptibility to NAFLD; however, its association with steatosis grade is inconsistent in the literature." (PMID 23176674, 2012). "However, in the livers of mice, neither inactivation nor overexpression of PNPLA3 resulted in steatosis." (PMID 38674929, 2024). "Focusing on the impact of the PNPLA3 genotype on lifestyle interventions in NAFLD patients, one study showed that mutated patients were more sensitive to the beneficial effect of lifestyle modification on steatosis reduction, rather than wildtype patients." (PMID 35276911, 2022). "We then investigated liver graft mRNA gene expression of PNPLA3 and APOB, involved in Ld-MaS and VLDL metabolism, and of genes involved in cholesterol hepatic metabolism according to the presence and the predominant type of steatosis in the pre-ischemia biopsy before LT." (PMID 34198853, 2021). "Although PNPLA3 is mainly involved in triacylglycerol remodeling, it may directly precipitate fibrogenesis and carcinogenesis, irrespective of steatosis by impairing retinol release from HSCs." (PMID 34829753, 2021). "In HSC the variant PNPLA3 I148M alters retinol secretion, thus contributing to fibrogenesis and carcinogenesis, with a consequent increase of the risk of cirrhosis and HCC development, regardless of the predisposition to steatosis." (PMID 33578702, 2021). "Similarly, Pnpla3 is a TG hydrolase with LPA transacylase activity; however, the physiological relevance of Pnpla3 in TG metabolism remains ambiguous as targeted deletion of Pnpla3 does not impair TG hydrolysis or promote steatosis." (PMID 33013449, 2020). "Additionally, our data indicated that female SHROB rats elicited more efficient fatty acid transport (Cd36) and esterification (Pnpla3), and greater insulin sensitivity (higher phosphorylation of AKT and AMPK), all of which contributed to less severe steatosis." (PMID 30201044, 2018). "Modulation of serum adiponectin might be involved in mediating the susceptibility to steatosis, NASH, and hepatocellular carcinoma in carriers of the 148 M PNPLA3 variant without CHC, with potential therapeutic implications." (PMID 22898488, 2012). "A model that has been proposed that is consistent with the neomorph hypothesis is that PNPLA3-I148M sequesters CGI-58/ABHD5, a cofactor for the triglyceride hydrolase ATGL/PNPLA2, impairing triglyceride hydrolysis on cytosolic lipid droplets (LDs) and thereby driving steatosis." (PMID 38657050, 2024). "At bivariate analysis, niacin intake was lower in NAFLD subjects with steatosis ≥ 2 compared to those with low-grade or no steatosis (p < 0.05 at Wilcoxon, adj p = 0.02 vs steatosis < 2) and in PNPLA3 CG/GG carriers (p < 0.05 at Wilcoxon, adj p = 0.02 vs PNPLA3 CC)." (PMID 36937355, 2023). "Last, while the patatin-like phospholipase domain-containing protein 3 (PNPLA3) SNP rs738409 has mainly been studied in nonalcoholic fatty liver disease (NAFLD), studies in patients with CHC have shown an association with steatosis, fibrosis, and HCC, although data are conflicting." (PMID 25504078, 2014).
steatosis (continued). "Interestingly however, the rs12979860 CC genotype protected form steatosis in patients positive, but not in those negative for the PNPLA3 G variant at risk, suggesting that an interaction occurs between IL28B and PNPLA3 genotypes in the pathogenesis of steatosis in CHC non genotype-3 patients." (PMID 23394097, 2013). "Low adiponectin levels were associated with steatosis, age, male gender, dyslipidemia, cirrhosis, and viral genotype 4 (patients carrying genotype 4 were all males), nearly associated with ADIPOQ genotype (p = 0.068), but not with PNPLA3 I148M genotype (p = ns)." (PMID 22898488, 2012). "Modulation of serum adiponectin might be involved in mediating the susceptibility to steatosis, NASH, and hepatocellular carcinoma in carriers of the 148 M PNPLA3 variant without CHC, with potential therapeutic implications, but additional studies are required to confirm this hypothesis." (PMID 22898488, 2012). "The ability of PNPLA3 I148M to promote steatosis was weakened in mice lacking liver CGI-58, further consolidating the key role of CGI-58 in mediating the action of PNPLA3 I148M." (PMID 37753315, 2023). "We generated double knockout (DKO) mice lacking both Mgl and Pnpla3; DKO mice were compared to Mgl−/− after a challenge by high-fat diet (HFD) for 12 weeks to induce steatosis." (PMID 33672787, 2021).
liver disease (143 papers, 2012 to 2026). "Our study, therefore, uncovers new therapeutic opportunities for targeting inflammation and fibrosis in patients with PNPLA3-associated liver disease." (PMID 41564367, 2026). "Mislocalization of certain LD-targeted membrane proteins, including HSD17B13 and PNPLA3, is implicated in metabolic dysfunction-associated steatotic liver disease." (PMID 42191894, 2026). "In this context, increasing attention has been given to intronic variation within the PNPLA3 locus as a potential contributor to interindividual and population-specific differences in liver disease susceptibility." (PMID 41516346, 2026). "Nonetheless, GWAS studies across populations have identified mutations in PNPLA3 as contributing to steatotic liver disease and liver damage beyond the rs738409 variant." (PMID 41516346, 2026). "The risk allele encodes the I148M variant of the PNPLA3 lipase which facilitates hepatic steatosis and increases the risk for liver diseases, including MASLD and HCC." (PMID 41487453, 2026). "Available evidence shows a robust association between PNPLA3 variants and the severity of liver disease and hepatic outcomes; conversely, contrasting evidence is available about the impact of the PNPLA3 G allele on the risk of extrahepatic complications." (PMID 39412170, 2025). "A growing body of literature including our paper showed that both insulin resistance and the PNPLA3 risk allele can drive the progression of liver disease." (PMID 39801107, 2025). "The PNPLA3 rs738409 (p.I148M) polymorphism is the most prevalent genetic risk factor for metabolic dysfunction-associated steatotic liver disease progression and is influenced by fasting and feeding cycles." (PMID 40677694, 2025). "The risk was higher in MZ heterozygotes than in the carriers of variant alleles of liver disease-modifying genes, such as PNPLA3, TM6SF2 and MBOAT7." (PMID 41004464, 2025). "Polymorphisms in liver disease–risk genes such as PNPLA3 and TM6SF2 have been linked directly to liver metabolism." (PMID 40371650, 2025). "This is consistent with the observation that genetic variation in PNPLA3 confers susceptibility to hepatic fat content and liver injury, and it is associated with an earlier age of liver disease diagnosis." (PMID 40244110, 2025). "The growing understanding of the causal role of PNPLA3 I148M variant on liver disease severity has led to investigations on potential non‐invasive assessment of liver injury and fibrosis by gene‐including scores." (PMID 39412170, 2025). "Overall, these results confirm an increased susceptibility of PNPLA3 CG and GG carriers to develop more advanced liver disease." (PMID 40677694, 2025). "For instance, patatin-like phospholipase domain-containing protein 3 (PNPLA3) variants are significantly associated not only with hepatic disorders but also with diabetes, insulin resistance, metabolic syndrome, and related cardiovascular events." (PMID 41252444, 2025). "Variants in the PNPLA3 gene, especially the I148M polymorphism, have been implicated in increased susceptibility to liver disease and MASLD in particular." (PMID 41157259, 2025). "PNPLA3-Ile148Met (rs738409, patatin-like phospholipase domain-containing protein 3) is the most impactful genetic risk factor for steatotic liver disease." (PMID 41244049, 2025). "The association for liver disease protection among statin users was evident for HCC among carriers heterozygous for the PNPLA3 rs738409 risk allele (HR, 0.31; 95% CI, 0.11-0.85; P = .02) (eTable 6 in Supplement 1)." (PMID 37358849, 2023). "We observed that patients who were minor homozygous for genetic variants previously related to predisposition to liver disease (PNPLA3 and MBOAT7) had increased phase I enzyme activity." (PMID 37686209, 2023).
liver disease (continued). "Similar to the results in the general population, Omega-3 intake resulted in a 27.1% risk reduction of incident liver disease in heterozygous carriers of the minor allele of PNPLA3 rs738409 (HR = 0.729; 95% CI: 0.602, 0.884; p = 1.0 × 10−3)." (PMID 37538264, 2023). "Can genotypic information about the patatin-like phospholipase domain-containing protein 3 (PNPLA3) I148M variant, a major genetic variant in liver diseases, play a role in stratifying the risk of individuals with alcohol consumption and obesity?" (PMID 36190732, 2022). "Conversely, our previous study did not identify acquired somatic mutations in genes with strong germline associations with liver disease (e.g. PNPLA3, TM6SF2)." (PMID 35474605, 2022). "The G/G‐genotype of PNPLA3 was associated with a higher rate of developing severe liver disease compared with the C/C genotype in both the crude analysis (HR 2.14, 95% CI = 1.17–3.91) and when adjusting for age, sex, T2D and BMI (aHR 2.27, 95% CI = 1.15–4.47)." (PMID 36166317, 2022). "Additional studies are needed in populations with different genetic ancestry to validate the findings and to incorporate PNPLA3 I148M variant information in surveillance and/or chemoprevention of liver diseases." (PMID 36190732, 2022). "After up to 40 years of follow‐up, the PNPLA3 G/G genotype was associated with a higher rate of severe liver disease (adjusted hazard ratio [aHR] 2.27, 95% CI = 1.15–4.47) compared with the C/C variant." (PMID 36166317, 2022). "The most common and strongest genetic risk factor for steatotic liver diseases is a common missense variant of PNPLA3 (patatin-like phospholipase domain-containing protein; rs738409), PNPLA3(I148M)." (PMID 36611868, 2022). "According to participants' testimonies, discovering their PNPLA3 status allowed them to assess their risk for liver diseases and the implications to more severe stages of disease in the NAFLD continuum." (PMID 36684893, 2022). "In a recent study on more than 80 000 obese individuals from the UK biobank with similar outcome measures, the PNPLA3 C > G allele was shown to increase the risk of severe liver disease 1.6‐fold." (PMID 36166317, 2022). "Accordingly, a recent large prospective UK Biobank study consisting of 22,812 T2D participants demonstrated that PNPLA3 rs738409 was independently associated with an increased risk of severe liver disease during follow-up." (PMID 35630668, 2022). "We observed a clear association between the PNPLA3 rs738409 G-allele carriage and pre-treatment severity of hepatic dysfunction and portal hypertension, which is in line with the previous literature." (PMID 33917196, 2021). "In recent studies, PNPLA3 has been identified as the central risk allele influencing liver disease severity in NAFLD." (PMID 33804385, 2021). "The primary focus of this pilot study was the determination of the gene frequency of polymorphisms in the PNPLA3 gene, which is implicated as an important factor in liver disease progression in patients with ASH and NAFLD/NASH." (PMID 33800964, 2021). "The association between alleles of PNPLA3 and the histological severity of hepatic disease has also been confirmed." (PMID 34833467, 2021). "Patatin-like phospholipase domain-containing 3 gene (PNPLA3) and its variants (PNPLA3 I148M) have been confirmed to be closely related to the occurrence of liver disease." (PMID 34476007, 2021). "Patients carrying the PNPLA3 minor allele had more advanced liver disease prior to antiviral therapy, confirming its impact on liver disease progression." (PMID 33917196, 2021). "This article reviews the discovery and role shaping research progress and challenges about PNPLA3, and mainly elaborates the role of a non-synonymous variant of PNPLA3 (rs738409, I148M) in liver disease and related diseases." (PMID 34476007, 2021). "This review mainly describes the pathophysiological effects of PNPLA3 and its variants, and their roles in the progression of liver disease and its complications." (PMID 34476007, 2021).